HIF1A (hypoxia inducible factor 1 subunit alpha)
Diseases named in the same sentence as HIF1A in open-access papers (continued):
Sharing a sentence is not in itself a finding about the gene and the disease.
tumor (continued). "In cancer cells, these Complex I-dependent events contribute to tumor formation, acquisition of resistance to cell death stimuli, and promotion of metastasis by increasing ROS levels, inducing HIF1α signaling, and inhibiting mTORC1 signaling and EMT induction." (PMID 28642839, 2017). "Immunohistochemical analysis also demonstrated decreased NF-κB, STAT3, and HIF-1α expression levels in the tumor tissue treated with miR-302b." (PMID 28467773, 2017). "Hypoxia can interfere with T cell effector function by selectively upregulating programmed death-ligand 1 (PD-L1) expression on both tumor cells and myeloid-derived suppressor cells (MDSCs) in a HIF-1α-dependent manner." (PMID 28348554, 2017). "This has led to the generally accepted idea that increased expression of HIF-1α actively drives tumor growth and progression by regulating the expression of important target genes." (PMID 28404916, 2017). "A number of studies have shown high tumor expression of HIF-1α as adverse prognostic features in head and neck SCCs, but this has not been a universal finding." (PMID 28099149, 2017). "In tumor cells grown in normoglycemic medium, 64B abrogated hypoxia (1% O2)-induced HIF-1α protein accumulation, whereas HIF-1β remained unaltered." (PMID 29245898, 2017). "At the same time, HIF-1α, ki-67, a commonly used tumor cell proliferation index, and MVD are biologically and clinically relevant." (PMID 28099905, 2017). "HIF-1α can function as a tumor suppressor by up-regulating genes such as Ndrg1 and Selenbp1, whose loss is associated with poor prognosis in human epithelial malignancies." (PMID 28572533, 2017). "In particular, as anticipated, we found that the effect of AZD5363 on pro‐angiogenic tumour signalling revealed levels of HIF‐1α were significantly reduced in drug‐treated tumours, as were tumour‐derived VEGF levels." (PMID 29084756, 2017). "This analysis indicated that in the tumor region, which had a higher level of HIF-1α, EPO and EPOR also expressed higher and cells grew faster." (PMID 29238266, 2017). "In order to explore the possible mechanism that how PHD3 or FIH function as tumor suppressor, HIF-1α, Ki-67 and MVD were considered." (PMID 28099905, 2017). "HIF-1α delayed premature senescence, and thus activation of HIF-1α in tumor cells would limit premature senescence and confer a biological advantage on these cells." (PMID 27788497, 2017). "Here, the authors show that HIF-1α deletion in NK cells impairs NK cytotoxic activity but inhibit tumour growth by decreasing the infiltration of NK cells that express angiostatic soluble VEGFR-1, thus resulting in non-functional angiogenesis." (PMID 29150606, 2017). "In the last weeks, the increase in Ki67 expression was also inversely correlated with HIF1α in both neoplasms." (PMID 28386296, 2017). "In human GBM surgical specimens, tumor cells palisading around necrotic areas are exposed to hypoxic stimuli and induce dramatic upregulation of HIF-1α." (PMID 29207533, 2017). "The potential role of HIF-1a in tumor development was first identified from its observed overexpression in a broad range of tumor types and its involvement in key aspects of tumor development." (PMID 28449718, 2017). "We measured the combination effect of BA/CDM on tumor cell growth through ROS formation and HIF1α pathway suppression." (PMID 29212263, 2017). "The present study aims to elucidate the dual effects of plasminogen kringle 5 (K5) on tumour angiogenesis and apoptosis induction by targeting hypoxia-inducible factor 1α (HIF-1α) and GRP78." (PMID 29072683, 2017). "High expression levels of HIF-1α, a marker of tumor hypoxia, have been reported in patients with OSCC." (PMID 28521842, 2017). "In the local hypoxic areas of the tumor microenvironment HIF-1α triggers CXCL12 (SDF-1) expression which in turn increases migration, adhesion, and homing of CXCR4+ progenitors." (PMID 28197019, 2017).
tumor (continued). "The nuclear expression of HIF-1α was decreased in UT-SCC-14 tumours after cetuximab treatment but was mostly unchanged in tumours from the UT-SCC-2." (PMID 28756482, 2017). "Overall, these results suggest that fascaplysin inhibits TRKA and VEGFR2 and downregulates survivin and HIF-1α, resulting in suppression of tumor growth." (PMID 28961193, 2017). "In this research, it was confirmed that miR-142, known as tumor-suppressive miRNA, had a regulatory relationship with an oncogene, HIF-1α." (PMID 28069592, 2017). "Wwox’s role in cancer progression is one of the intensely debated concepts, because of its double nature in primary tumor growth and metastatic process, and its relation with HIF-1α expression/HIF-1 activity." (PMID 28045433, 2017). "Collectively, these studies have shown that NRF2 inhibition can suppress tumor angiogenesis, possibly through inhibiting hypoxia-induced activation of HIF-1α signaling." (PMID 29268703, 2017). "RNAs were extracted then amplified by RT-qPCR for the 26 up-regulated genes of interest in tumor zones delimited after HIF-1α immunostaining and compared to microarray fold changes obtained in the hypomel signature derived from cell lines." (PMID 29312568, 2017). "SIM2l-overexpressing CvSCC cells showed both cell growth inhibition and sensitivity to ROS in a 3D culture, and SIM2l-overexpressing tumors suppressed HIF-1α expression, angiogenesis, and tumor progression in vivo." (PMID 29109451, 2017). "Hypoxia-inducible factor-1 α (HIF-1α) is a transcription factor that is dominantly expressed under hypoxia in solid tumor cells and is a key factor that regulates tumor." (PMID 28165392, 2017). "Co-localization of Ang II and HIF-1α proteins in the cytoplasm of hypoxic tumor cells was also detectable in confocal laser scanning microscopy." (PMID 28205588, 2017). "It has also been suggested that hypoxia induces HIF-1α-dependent accumulation of lipid droplets in tumor cell lines, where de novo FA synthesis is repressed." (PMID 29295482, 2017). "Targeting of HIF-1α or de novo pyrimidine biosynthesis, together with gemcitabine administration exert a strong anti-tumor effect." (PMID 29156578, 2017). "The hypoxic microenvironment contributes to tumour progression through the stabilization of the potent transcriptional factor HIF-1α." (PMID 29072683, 2017). "MYC and HIF-1α are known to cooperatively activate glycolysis to generate adequate energy for tumor cells, resulting in chemo-resistance through the upregulation of many genes relevant to glucose metabolism." (PMID 28055963, 2017). "Under these circumstances, the activity of PHD is limited, which indirectly strengthens HIF-1α activation and stabilization, thus triggering overexpression of target genes related to proliferation, cell migration and tumor invasion as clarified above." (PMID 28881853, 2017). "Double immunofluorescence technique revealed that iNOS and HIF-1α were co-localized in tumor tissues." (PMID 28825631, 2017). "A primary response of tumor cells to hypoxia is to upregulate HIF1-α and its downstream targets, principally the pro-angiogenic VEGF." (PMID 28521819, 2017). "Hydroxylated HIF-1α is recognized by the tumour suppressor von Hippel-Lindau protein, which targets HIF-1α for degradation." (PMID 29100336, 2017). "Tumor cell migration capacity is also enhanced by activation of the HIF1-α pathway, which in turn regulates CA activity." (PMID 28235409, 2017).
tumor (continued). "Given the defect in NK cell infiltration in HIF-1α KO mice, reduced sVEGFR1 levels in tumours from HIF-1α KO mice are most likely a result of a lower number of sVEGFR1-expressing NK cells." (PMID 29150606, 2017). "NRF2 is an upstream regulatory gene of HIF-1α, and also believed to play an active role in tumor angiogenesis." (PMID 29268703, 2017). "Expression of the transcription factor HIF1A by tumor cells inhibits osteoblast differentiation and enhances the differentiation and maturation of osteoclasts, in part via VEGF induction." (PMID 28319320, 2017). "HIF1α activity is also found to be significantly upregulated in various types of cancer, as a result of genetic alterations and hypoxia within the tumor tissue." (PMID 28057028, 2017). "We found that dextran+ area distributed outside tumor vessel was significantly reduced by 7.32 × 104 pixels in shRNA-HIF-1α-4T1 tumor, suggesting an inhibitory effect of HIF-1α blockade on vessel leakage." (PMID 29088755, 2017). "Some studies have shown that inhibiting the expression of HIF-1α or GLUT-1 alone increased tumor cell apoptosis." (PMID 28410229, 2017). "Compound 12 can be a novel inhibitor of HIF-1α by accelerating its degradation, and shows much potential as an anti-cancer agent through its ability to suppress tumor growth and angiogenesis." (PMID 27999195, 2017). "Firstly, HIF1α expression was detected in tumor sample collected from mice fed in 10% O2 through immunohistochemistry." (PMID 28427209, 2017). "MiR-1 suppressed aerobic glycolysis and tumor cell proliferation via inactivation of Smad3 and targeting HIF-1α, leading to reduce HK2 and MCT4 expression, which illustrated a novel pathway to mediate aerobic glycolysis in cancer cells." (PMID 28471448, 2017). "The authors identified CD45- CD90+ CTCs in 91% of samples and demonstrated that this cell population expressed key stem-like genes including Bmi1, CD44, Oct4, Notch1, Wnt3a, Stat3, and HIF-1a compared to CD90+ tumor-tissue cells." (PMID 27738343, 2017). "This striking uncoupling of angiogenesis and tumour oxygenation in HIF-1α KO mice was confirmed in an independent experimental setup." (PMID 29150606, 2017). "Microvascular counting in tumor tissues revealed that MVD in HIF-1α/siRNA group (7.3±1.1) was obviously less than that in SCR/siRNA group (17.2±3.2) (P<0.05)." (PMID 28523034, 2017). "al has shown that HIF-1α regulates miR-210 expression through binding to the hypoxia-responsive element (HRE) in the region of miR-210 promoter in tumor initiation." (PMID 28173803, 2017). "Cells within the tumor become hypoxic as the tumor mass increases, resulting in activation of HIF-1α to induce various malignant phenotypes." (PMID 28038441, 2017). "The hypoxia-inducible factor 1α (HIF-1α) and its microRNA target, miR-210, are candidate tumor-drivers of metabolic reprogramming in cancer." (PMID 28036268, 2017). "Because of the key role of hypoxia and HIF- 1α in tumor angiogenesis as well as in tumor progression, HIF-1α or HIF-1α pathways have become an interesting target in anticancer research." (PMID 29271940, 2017). "Further, upregulation of HIF1-α in the hypoxic tumor microenvironment upregulates CAIX, its downstream target." (PMID 28235409, 2017). "HIF-1α is the key molecule to maintain the adaptive response of the cells to reduced oxygen level, making the cells capable of surviving under a hypoxic tumor microenvironment." (PMID 29238266, 2017). "HIF-1α expression was detected in tumor tissues in all patients, and correlated with iNOS expression and 8-oxodG formation." (PMID 28825631, 2017). "HIF1, consisting of HIF1α and HIF1β subunits, is a key mediator of the cell response to hypoxia, and its high expression correlates with poor prognosis in various tumor types." (PMID 28061479, 2017).
tumor (continued). "We cannot exclude the possibility of involvement of extrinsic microenvironmental factors such as hypoxic induction of HIF-1α that contributes to GLUT1 expression especially when tumours become hypoxic at the advanced stages." (PMID 28548087, 2017). "This combined analysis provides insights into the mechanisms of HIF-1α/miR-210 regulation in normal and tumor tissues potentially useful for understanding the pathogenesis of cancer and other diseases sharing similar underpinnings." (PMID 28036268, 2017). "Collectively, our data indicate that IDF-11774 suppressed hypoxia-induced HIF-1α accumulation and repressed tumor growth by targeting energy production-related cancer metabolism." (PMID 28569777, 2017). "Of note, hypoxia is a potent driver of tumor invasiveness via activation of the hypoxia inducible factor (HIF)-1α, the expression levels of which directly correlate with tumor size and inversely correlate with disease-free and overall survival in iCCA." (PMID 28098760, 2017). "This evidence showed that the increase in the expression of HIF-1α in the tumor and in the cells in response to Minnelide treatment was due to the lack of co-factor αKG that was required for the activity of the enzymes PHD1-3." (PMID 28801636, 2017). "We found that HIF-1α deletion resulted in impaired expression of a set of proteins critically involved in CTL-mediated tumor rejection." (PMID 29136509, 2017). "Genetic inactivation of β-catenin or HIF-1α severely reduced stem cell frequency, while having minimal impact on the growth or viability of bulk tumor cells, implying that elements of Wnt and Hif pathways specifically support leukemic stem cells." (PMID 28872614, 2017). "Hypoxia-inducible factor-1α (HIF-1α) is a key transcription factor induced by hypoxia that has been reported to correlate with a poor prognosis, local tumor recurrence, and distant tumor metastases after RT." (PMID 28348554, 2017). "HIF-1α is an oxygen-dependent transcriptional factor, which plays crucial roles in the tumor progression." (PMID 29100347, 2017). "The hypoxia-induced von-Hippel-Lindau (VHL)–hypoxia-inducible factor 1 alpha (HIF1α)–VEGF-axis plays a crucial role in the onset of tumor angiogenesis, and diverse miRNAs have been identified to modulate these players." (PMID 28474282, 2017). "In agreement with the in vitro data, the simultaneous analysis of CAIX and HIF-1α protein levels in SCC tumor tissues revealed that the two proteins are jointly co-expressed in cancer cells." (PMID 28099149, 2017). "SIRT2 is selective for deacetylation of tubulin and contributes to HIF1-α to modulate hypoxia-dependent responses in tumor cells." (PMID 28503576, 2017). "The effects of ACF on cancer cells were first reported 50 years ago22, but research interest peaked in 2009, when a study of 336 drugs singled out ACF as the most potent HIF-1α inhibitor with effective tumor growth inhibition in a prostate cancer model." (PMID 29097800, 2017). "Our analysis of SqCC and ADC KL tumours identified that higher p-AKT, p-4EBP1 and p-S6 expression in SqCC is associated with higher HIF-1α and GLUT1 expression in SqCC tumours compared to ADC tumours." (PMID 28548087, 2017). "Amelioration of tumor hypoxia by metformin treatment suppresses excessive angiogenesis via inhibition of HIF-1α-AAFs signaling." (PMID 29088755, 2017). "Immunoblots showed higher expression of HIF-1α and centrosomal proteins in both tumor types in comparison with their normal adjacent tissues." (PMID 28272508, 2017). "The development of tumor specific HIF-1α inhibitor, which has a reduced off-target effect compared to chemotin, is warranted." (PMID 28055963, 2017). "In our model, HIF1α was overexpressed in the early stages, indicating that the angiogenic process is constitutively active in the xenotransplanted tumour." (PMID 28386296, 2017). "Collectively, these data indicated that HIF-1α was a direct target of miR-1 and had a critical role in tumor glycolysis." (PMID 28471448, 2017).
tumor (continued). "It’s worth noting that miR-210-3p has been broadly demonstrated to be a direct target of HIF-1α in a variety of tumor cells." (PMID 28693582, 2017). "Our results show that MNPs and MF elevate the temperature in vitro in tumor cells, thereby increasing the expression of ROS as well as HSPs and Hif-1α." (PMID 28580034, 2017). "K5 promoted the sumo/ubiquitin-mediated proteasomal degradation of HIF-1α by upregulating von Hippel-Lindau protein under hypoxia, resulting in the reduction of vascular endothelial growth factor and thus suppressing tumour angiogenesis." (PMID 29072683, 2017). "WB analysis showed HIF-1α expression in control 58As9 tumours, suggesting hypoxic regions persisted." (PMID 28978999, 2017). "Immunocytochemical staining after cetuximab treatment shows a significantly decreased expression of EGFR, pEGFR, Ki67, CAIX and nuclear HIF-1α in UT-SCC-14 tumours compared to untreated controls." (PMID 28756482, 2017). "Third, tumor starts to experience hypoxia when size reach 2 mm2 and hypoxia induces HIF-1α accumulation." (PMID 29088755, 2017). "Twenty-four hours after the injections, tumor tissues were collected to identify HIF-1α expression using immunohistochemistry." (PMID 28937321, 2017). "VEGF, an immediate downstream target gene of HIF-1α playing a critical role in tumor angiogenesis, was increased in cell lysates and cell culture supernatants of GSC cultured under hypoxic conditions." (PMID 28410215, 2017). "Again, we found a decrease in angiostatic sVEGFR1 levels in tumours from HIF-1α KO mice, whereas VEGF expression was similar across genotypes." (PMID 29150606, 2017). "Through its major downstream target STAT3 several tumor promoting pathways are activated, including HIF1-α and VEGF." (PMID 28859644, 2017). "Anti-angiogenesis therapy, such as bevacizumab treatment, has an indirect effect on tumor cells but leads to the activation of the hypoxia HIF-1α program resulting in the upregulation of drug resistance pathways." (PMID 28402937, 2017). "When cells are hypoxic, the PI3k/Akt/HIF1α signaling pathway is activated to regulate tumor glucose metabolism." (PMID 28903449, 2017). "Hypoxia inducible factor 1α (HIF1α) regulates tumor metabolism by repressing respiration, while promoting glycolysis." (PMID 28206987, 2017). "The levels of CD34 and HIF-1α in the tumour and para-tumour groups and in the tumour and normal groups are significantly different." (PMID 29072683, 2017). "Hypoxic tumor microenvironment elicits stabilization of HIF-1α and subsequent induction of VEGF expression." (PMID 28052029, 2017). "A series of gene knockdown and overexpression experiments revealed that SIM2l acts as a tumor suppressor gene via transcriptional suppression of HIF1A and decreased radiation resistance and tumor growth in CvSCC." (PMID 29109451, 2017). "Next, we evaluated response to treatments by measuring the expression levels of MTA1 and HIF‐1α in tumor tissues." (PMID 29024573, 2017). "Elevated AKT/mTOR activity and HIF-1α expression were also evident in SqCC cells and xenograft tumours." (PMID 28548087, 2017). "Adaptation to hypoxia is a driving force for tumor progression whereby hypoxia stimulates the hypoxia-inducible factor 1α (HIF-1α)-mediated LOX expression." (PMID 28425924, 2017). "To validate specific upregulation of HIF-1α in NQO1-expressing tumours, we analysed HIF-1α protein levels in tumour tissues." (PMID 27966538, 2016). "The absence of Nrf2 can lead to a decline in capillary density of tumor tissues by imposing a blockade to HIF-1α signaling." (PMID 27869147, 2016). "Since the critical role of HIF-1α in tumor progression and metastasis, inhibition of HIF-1α was considered as a promising therapeutic strategy." (PMID 26856989, 2016). "To determine the functional contribution of NQO1 to HIF-1α expression and tumour growth in vivo, we evaluated the growth rate of NQO1-knockdown or overexpressing RKO xenografts in female BALB/c nude mice." (PMID 27966538, 2016).